CCS (copper chaperone for superoxide dismutase)
Diseases named in the same sentence as CCS in open-access papers (continued):
Sharing a sentence is not in itself a finding about the gene and the disease.
uterine corpus endometrial carcinoma (1 paper, 2019). A endometrial carcinoma (disease) that involves the body of uterus. "It seems that neither the Atox1 nor CCS gene are often mutated in any of the cancers examined, with the highest mutation frequency for CCS and Atox1 observed in uterine corpus endometrial carcinoma (UCEC) (1.5%) and liver hepatocellular carcinoma (LIHC) (0.27%) malignancies, respectively." (PMID 31575544, 2019).
tumor (14 papers, 2019 to 2026). "According to the results of the experimental validation of the samples, three genes (SDHB, ULK1, and CCS) had the highest risk scores and the same trend of the gene expression between tumor and normal tissues when compared with DEGs in TCGA, which means that our model has consolidated verification." (PMID 36505872, 2022). "Specifically, the expression levels of SLC6A3, MITD1, and PDHA1 exhibited an increasing trend with tumor pathological stage, whereas CCS, LIPT2, PDHB, and PDHA1 displayed a decreasing trend in response to radiation therapy." (PMID 38159255, 2023). "Providing that Atox1 and CCS copper chaperones are essentially engaged in trafficking of cisplatin and in its targeting to specific molecules, their cognate gene mutations, deletions or downregulations may render tumor cells refractory to cisplatin-based therapy." (PMID 31575544, 2019). "Copper chaperone for superoxide dismutase (CCS) is a critical component of oxidation–reduction system and functions as a potential tumor promoter in several cancers." (PMID 31024318, 2019). "Tumor cells control the expression of CCs to draw in inflammatory cells and use these elements to accelerate the development and spread of tumors, which implies that CCs and CC receptors in an inflammatory TME can support the proliferation of tumors." (PMID 37373025, 2023). "The following three kinds of CCs, extracellular space, synaptic vesicle membrane and extracellular exosome, may also play important roles in tumor development and its micro-environmental manipulation." (PMID 31130992, 2019). "Interestingly, pharmacological intervention with the anti-cancer drug cisplatin indicates the major contribution of CCS copper chaperone to cisplatin's cellular trafficking, and presumably to tumor resistance often acquired during chemotherapy." (PMID 31575544, 2019). "All these findings indicate the potential role of CCS in tumor formation and progression." (PMID 31024318, 2019). "Depending on tissue settings and genetic contents, Atox1 and CCS chaperones can control cisplatin trafficking routes and targeting efficiencies, thus indicating their essential contribution to acquired resistance of tumor cells to cisplatin-containing therapeutic regimens." (PMID 31575544, 2019). "TRIM22 attenuates BC progression by targeting the JAK-STAT/STAT3 axis through CCS-mediated degradation, resulting in suppressed STAT3 phosphorylation and reduced tumor invasiveness." (PMID 41601694, 2026). "Out of the identified regulators, six genes (SLC6A3, MITD1, CCS, LIPT2, ATOX1, and GLS) showed increased expression in tumor tissues, while PDHB had higher expression in normal tissues." (PMID 38159255, 2023). "Thus, CCS may be a therapeutic strategy to suppress tumor growth and metastasis." (PMID 31024318, 2019). "Moreover, the result of Western blots showed that the expressions of SDHB and CCS were downregulated and that of ULK1, CDKN2A, and CMC1 were upregulated in tumor tissues compared with normal tissues." (PMID 36505872, 2022).
cancer (10 papers, 2018 to 2024). A tumor composed of atypical neoplastic, often pleomorphic cells that invade other tissues. "Hence, before applying a cisplatin-dependent regimen to a cancer patient, the thorough mutational and expression profiling of (among others) Atox1 and CCS genes are strongly advised." (PMID 31575544, 2019). "Cancer cells upregulate several copper chaperones such as the copper chaperone for SOD1 (CCS), which binds cytosolic copper and transfers it to SOD1." (PMID 34390123, 2021). "Disruption of copper trafficking by pharmacologic inhibition of CCS has been shown to have therapeutic effects against a variety of cancers, indicating that proper trafficking is needed for cancer cell proliferation." (PMID 34390123, 2021). "Interestingly, it may be the CCS and/or Atox1 absence (or downregulation, or mutation-driven loss of function) that is critically implicated in drug resistance mechanisms, being frequently observed during cancer chemotherapy." (PMID 31575544, 2019). "Remarkably, all 12 different cancers examined were shown to carry low levels of Atox1 and CCS gene expression, thereby suggesting their potential ability to develop resistance against cisplatin during malignancy clinical management." (PMID 31575544, 2019). "A recent study also demonstrated that small molecules that inhibit the human copper trafficking proteins Atox1 and CCS significantly reduce proliferation of cancer cells, suggesting copper chaperones as new targets for the development of anticancer therapies." (PMID 29320492, 2018). "Furthermore, 6 out of 12 (50%) cancers are characterized by detectably downregulated Atox1 and/or CCS gene activities." (PMID 31575544, 2019). "Indeed, several types of different human cancers analyzed via employment of the TCGA bioinformatics platform are characterized by strikingly diminished levels of Atox1 and CCS gene expression compared to control." (PMID 31575544, 2019). "We started by characterizing the basal level of Cu-dependent proteins which are reported to play a role in cancer development and spreading (i.e., ATP7A, LOXL2, CCS and Cytochrome c Oxidase) in the cells under study." (PMID 36454513, 2023). "Indeed, cancer cells upregulate several Cu2+ chaperones such as the copper chaperone for SOD1 (CCS), which binds cytosolic Cu2+ and transfers it to SOD1, and pharmacological disruption of this process can have therapeutic effects on cancer as it reduces uncontrolled cell proliferation." (PMID 37132605, 2024). "Strikingly, regarding their differential expression in 12 out of the 14 cancers analyzed, neither Atox1 nor CCS genes are found significantly upregulated, with the comparably strongest expression levels being respectively measured in UCEC and BRCA malignancies." (PMID 31575544, 2019).
infection (5 papers, 2012 to 2025). The state of being infected such as from the introduction of a foreign agent such as serum, vaccine, antigenic substance or organism. "The data showed that the intestinal microbiota of OcB/Dem mice was more variable after infection in comparison to the intestinal microbiota of CcS/Dem strains, which was more stable after infection." (PMID 38240984, 2024). "In liver, infection induced significant increases of Gbp2b/Gbp1 mRNA in strains of CcS/Dem series, CcS-5, and CcS-16." (PMID 29467757, 2018). "An animal model of TBE based on BALB/c-c-STS/A (CcS/Dem) recombinant congenic mouse strains showing different severities of the infection in relation to the host genetic background was developed." (PMID 23805778, 2013). "This differs from increase of serum levels of IL-4, IFNγ and IL-12 observed in CcS/Dem strains after 8 weeks of infection." (PMID 22679519, 2012). "The differences between parental strains and CcS/Dem strain CcS-20 persist after L. major infection, whereas the differences between expression of parents and CcS-5 and CcS-16 and between parent B10 and the strain B10.O20 disappear after infection." (PMID 29467757, 2018). "Only a few males of the strains CcS-18 and CcS-20 developed small nodules at the site of infection." (PMID 22679519, 2012). "The presence of parasites after 21 weeks of infection was detected in females of the strains BALB/c 33.33% (2 out of 6), CcS-3 66.67% (4 out of 6), CcS-11 42.86% (3 out of 7), CcS-16 71.43% (5 out of 7), CcS-18 66.67% (2 out of 3) and CcS-20 75% (3 out of 4)." (PMID 22679519, 2012).
neurodegenerative disease (2 papers, 2013 to 2024). A disorder of the central nervous system characterized by gradual and progressive loss of neural tissue and neurologic function. "All three functions “poorly characterised” functions, “metabolism” and “neurodegenerative diseases” were significantly higher in the colon microbiome of infected susceptible CcS/Dem strains." (PMID 38240984, 2024).
psychiatric disorder (2 papers, 2024 to 2025). A disorder characterized by behavioral and/or psychological abnormalities, often accompanied by physical symptoms. "The genes BCHE and CCS were implicated in multiple psychiatric disorder–cognition associations." (PMID 40002349, 2025). "CCS may form complexes with zinc ions, playing a crucial regulatory role in psychiatric disorders, including influencing neurotransmitter synthesis and release." (PMID 38637810, 2024).
CCS also shares sentences with these, for which no sentence is quoted: hepatocellular carcinoma (2 papers); and neck cancer (1); breast invasive carcinoma (1); breast tumors (1); carpal tunnel syndrome (1); esophageal cancer (1); gastrointestinal stromal tumor (1); gestational diabetes mellitus (1); head/neck cancer (1); Intellectual disability (1); invasive ductal carcinoma (1); latent infection (1); myxoma (1); ovarian carcinoma (1); protein-misfolding diseases (1); schizophrenia (1); triple-negative breast carcinoma (1).